TSPO (translocator protein)
Diseases named in the same sentence as TSPO in open-access papers (continued):
Sharing a sentence is not in itself a finding about the gene and the disease.
temporal lobe epilepsy (7 papers, 2019 to 2026). A localization-related (focal) form of epilepsy characterized by recurrent seizures that arise from foci within the temporal lobe, most commonly from its mesial aspect. "Background/Objectives: This study explored the heterogeneous distribution pattern of translocator protein 18kDa (TSPO)-PET/MRI using radioligand [18F] DPA-714 in temporal lobe epilepsy patients and identified clinical factors influencing imaging outcomes." (PMID 41750246, 2026). "Previous TSPO-PET imaging studies already reported focal TSPO-positive inflammatory tissue reactions in human temporal lobe epilepsy of various etiology, in different animal models of temporal lobe epilepsy, and with different TSPO-PET tracers." (PMID 37294768, 2023). "In contrast, in non-temporal lobe epilepsy cases, widespread TSPO-PET signals in cortical areas have occasionally been observed, although the underlying mechanisms remain unclear." (PMID 40836311, 2025). "In brain tissue samples from patients with temporal lobe epilepsy (TLE), TSPO expression is significantly increased in the hippocampus, particularly in the sclerotic regions ipsilateral to the seizure focus." (PMID 40836311, 2025).
alcohol (6 papers, 2015 to 2022). "Second, TSPO expression may be decreased due to potential loss of mitochondrial density with chronic alcohol exposure as has been reported to occur in preclinical models of alcoholism." (PMID 29777199, 2018). "The accumulation of TSPO is an indicator of the development of a number of diseases, and AX reduced the accumulation of TSPO in the liver of alcohol-dependent rats." (PMID 36290741, 2022). "Since we showed a change (increase) in the effects of PK11195 and PPIX in ethanol mitochondria compared with the control RLM, we suppose an existence of a special mechanism in chronic alcohol intoxication that activates the TSPO-dependent pathways of ligand action." (PMID 32722345, 2020). "Given the variety of known TSPO ligands, and the common mechanisms of various abusive substances, our studies suggest that TSPO might be a promising target to combat alcoholism as well as addiction to other drugs." (PMID 26241038, 2015). "Consequently, the TSPO may provide an important drug target for treatment of drug abuse and alcoholism which could be conveniently investigated with the current system." (PMID 26241038, 2015). "Since the research of our group, as well as literature data, indicate a tight relationship between TSPO and VDAC, we also investigated the effect of Cbx on VDAC level in the mitochondria of control animals and animals with chronic alcohol dependence." (PMID 34638588, 2021).
colorectal cancer (6 papers, 2015 to 2025). A primary or metastatic malignant neoplasm that affects the colon or rectum. "In previous studies, it has been shown that an overexpression of TSPO was associated with poor prognostic survival in patients affected with stage III colorectal cancer." (PMID 27054921, 2016). "The findings provide significant insights into the potential role of TSPO as a biomarker for tumor progression in colorectal cancer." (PMID 40550494, 2025). "Therefore, the new compound appears to be very promising in a receptor-mediated drug targeting context towards TSPO-overexpressing tumors, in particular colorectal cancer." (PMID 27347942, 2016). "However, these functions of TSPO may be reversed by the administration of TSPO-specific exogenous ligands in a variety of tumor types; furthermore, increased binding capacities of TSPO-specific ligands have been reported in colorectal cancer and a variety of different tumor types." (PMID 25663907, 2015).
Gliosis (6 papers, 2014 to 2025). Gliosis is the focal proliferation of glial cells in the central nervous system. "Chronic inflammation is a hallmark of many neurodegenerative disease and targeting of TSPO, a biomarker of gliosis, improved disease outcome in various preclinical model systems." (PMID 32483169, 2020). "Glial up-regulation of TSPO is a major hallmark of neurodegenerative diseases and various TSPO ligands have been developed as molecular markers to detect gliosis by means of Positron Emission Tomography (PET) imaging." (PMID 24397957, 2014). "Is translocator protein distribution volume (TSPO VT), an index of gliosis (an inflammatory change), measured by positron emission tomography, elevated in the brain after acute COVID-19 infection with sequelae of depressive and cognitive symptoms?" (PMID 37256580, 2023). "This is also the second study to assess the effect of minocycline on a measure of gliosis in brain in humans, applying a sample almost twice as large as the previous study which also measured TSPO VT." (PMID 34052828, 2021). "Translocator protein total distribution volume (TSPO VT), a brain marker mainly reflective of gliosis in disease, can be measured using positron emission tomography (PET)." (PMID 34052828, 2021). "Therapeutics to reduce gliosis, or more selectively the harmful effects of gliosis, may be helpful for COVID-DC, and gliosis-targeting treatments, such as TSPO and P2X7-binding medications, should be studied." (PMID 37256580, 2023). "Gliosis was measured by Iba-1, CD68, and TSPO, markers for microglia, as well as by the astrocytic marker GFAP." (PMID 34948098, 2021).
inflammatory bowel disease (6 papers, 2015 to 2024). A spectrum of small and large bowel inflammatory diseases of unknown etiology. "Overexpression of the mitochondrial translocator protein (TSPO) in the colon is a pathological feature observed in human ulcerative colitis (UC), a form of inflammatory bowel disease (IBD)." (PMID 36060674, 2022). "The purpose of the study was to validate [18F]DPA-714, a translocator protein (TSPO) 18 kDa radioligand, as a probe to non-invasively quantify the inflammatory state in inflammatory bowel disease (IBD) animal models." (PMID 25015387, 2015).
myocarditis (6 papers, 2021 to 2024). Myocarditis is a condition that is characterized by inflammation of the heart muscle (myocardium). "TSPO upregulation has been observed in cardiac diseases such as myocarditis, arrhythmia, atherosclerosis and cardiac hypertrophy." (PMID 38139248, 2023). "Previously, we have shown that TSPO is expressed primarily in CD11b+ immune cells in the hearts of men and male mice with myocarditis." (PMID 34445539, 2021). "This review aims to examine translocator protein (TSPO) and cyclooxygenase (COX-2) as biomarkers which are not limited to neuroinflammation but also associated with other types of inflammation attributed to tumor proliferation, autoimmune diseases, pulmonary diseases and myocarditis." (PMID 38139248, 2023).
age-related macular degeneration (5 papers, 2019 to 2025). Age-related loss of vision in the central portion of the retina (macula), secondary to retinal degeneration. "In retinal phagocytes, NOX1 is the primary source of ROS and depends on the translocator protein (TSPO) for activation; this NOX1-TSPO activity in microglia has been linked to neurotoxicity and abnormal retinal angiogenesis in age-related macular degeneration in a mouse model." (PMID 41008646, 2025). "First, targeting or knocking-out TSPO by synthesizing the ligand XBD173 confirmed that TSPO could inhibit phagocytic reactivity in the laser-induced mouse neovascular age-related macular degeneration model." (PMID 36278207, 2022). "There was a direct relationship between TSPO and the disease of age-related macular degeneration." (PMID 33924902, 2021). "TSPO in RPE cells was implicated to mediate cholesterol clearance from the subretinal compartment, and its age-related downregulation may promote progression of age-related macular degeneration." (PMID 30777091, 2019).
brain inflammation (5 papers, 2012 to 2025). "The magnitude of 11C-PK11195 binding is associated with progression, but it was unclear whether the serum metabolome, modestly linked to TSPO-defined brain inflammation, can predict MS progression." (PMID 40248672, 2025). "Additionally, BGU did not associate with TSPO availability, which was measured to assess brain inflammation." (PMID 40926735, 2025).
brain injury (5 papers, 2021 to 2024). Acute and chronic (see also brain INJURIES, CHRONIC) injuries to the brain, including the cerebral hemispheres, CEREBELLUM, and brain STEM. "Furthermore, we provide information about the longitudinal changes of TSPO PET findings and the underlying TSPO-positive cell populations after penetrating traumatic brain injury." (PMID 38255293, 2024). "However, the invasiveness and exposure to radiation required for TSPO PET imaging may limit its usage in clinical contexts as a biomarker for mild brain injuries." (PMID 34924026, 2021).
colitis (5 papers, 2017 to 2024). Inflammation of the colon. "Taken together, these results suggest that TSPO deficiency results in more severe colitis in a DSS-induced IBD mouse model." (PMID 35269479, 2022). "Our results identify a clear protective function for TSPO expression in colitis, deficiency of which results in exacerbated colonic inflammatory pathology." (PMID 36060674, 2022). "In this study, TSPO deficiency substantially exacerbated the inflammatory pathology associated with DSS-induced colitis." (PMID 36060674, 2022). "As the etiology and pathophysiology of UC remains to be fully defined, TSPO has been considered as a therapeutic target and investigated for reducing both stress and colon inflammation." (PMID 36060674, 2022). "To decipher the mechanisms leading to severe DSS-induced colitis in TSPO-KO mice, we analyzed local lymphocyte compositions in the colons of TSPO-KO and WT mice under physiological and pathological conditions." (PMID 35269479, 2022).
delirium (5 papers, 2021 to 2025). A disorder characterized by confusion; inattentiveness; disorientation; illusions; hallucinations; agitation; and in some instances autonomic nervous system overactivity. "The utility of astrocytic and microglial plasma biomarkers, including chitinase-3-like protein 1, translocator protein (18 kDa), CX3CL1 and CSF1, which are currently being trialled for other disorders should also be explored in the context of delirium." (PMID 39463449, 2025). "Molecules identified for this criterion from the RNAseq dataset with a known or possible involvement in encephalopathy and delirium included miR-320a-3p, ACHE, TSPO, and TIMP1, which interacted with MMP9." (PMID 34573990, 2021).
dementia with Lewy bodies (5 papers, 2019 to 2024). "Coincidently, our previous research with a different patient cohort shows that a significant reduction in 18-kDa translocator protein (TSPO) density—a marker of brain microglia activation—is observed in the SNc of AD cases and dementia with Lewy bodies (DLB) cases compared with age-matched controls." (PMID 32842621, 2020).
encephalitis (5 papers, 2014 to 2023). An acute inflammatory process affecting the brain parenchyma. "Future TSPO-PET/SPECT studies on viral neuroinflammation and related encephalitis should assess the contribution of immune cells on TSPO expression and employ appropriate image correction methods to subtract blood pool activity." (PMID 36348095, 2023). "The contribution of other immune cells to brain TSPO expression, especially in the context of viral encephalitis, has been grossly understudied." (PMID 36348095, 2023). "Therefore, brain TSPO-PET in ZIKV infection and other viral encephalitis models will need to be accompanied by appropriate image analysis methods, such as cardiac input correction, to separate blood pool activity from specific PET signals originating from the brain." (PMID 36348095, 2023).
head and neck squamous cell carcinoma (5 papers, 2021 to 2025). A squamous cell carcinoma that arises from any of the following anatomic sites: lip and oral cavity, nasal cavity, paranasal sinuses, pharynx, larynx, and salivary glands. "Sanni and colleagues sought to evaluate N,N-diethyl-2-(2-(4-([18F]fluoro)phenyl)-5,7-dimethylpyrazolo[1,5-a]pyrimidin-3-yl)acetamide ([18F]F-DPA), another TSPO tracer, in head and neck squamous cell carcinoma (HNSCC)." (PMID 33923410, 2021). "Moreover, [18F]FDPA can detect changes in TSPO expression after radiotherapy (RT) in head and neck squamous cell carcinoma (HNSCC) in mice." (PMID 39275061, 2024). "This study aimed to evaluate whether N,N-diethyl-2-(2-(4-([18F]fluoro)phenyl)-5,7-dimethylpyrazolo[1,5-a]pyrimidin-3-yl)acetamide ([18F]F-DPA) can reflect radiotherapy (RT)-induced changes in TSPO activity in head and neck squamous cell carcinoma (HNSCC)." (PMID 33340054, 2021). "Thus, the aim of this study was to comprehensively evaluate the TSPO tracer, N,N-diethyl-2-(2-(4-([18F]fluoro)phenyl)-5,7-dimethylpyrazolo[1,5-a]pyrimidin-3-yl)acetamide ([18F]F-DPA), in head and neck squamous cell carcinoma (HNSCC)." (PMID 33340054, 2021).
injury (5 papers, 2016 to 2023). Damage inflicted on the body as the direct or indirect result of an external force, with or without disruption of structural continuity. "That is, the ratio of uptake between the right and left putamen increased from 1.19 on day 1 to 1.30 on day 3, consistent with the relatively slow time-course of TSPO expression following brain injury." (PMID 32359360, 2020). "Overexpression of TSPO has been linked to the degree of damage in central and peripheral nervous tissues; as a consequence TSPO is used as an imaging tool for traumatic brain injury." (PMID 29897975, 2018).
Large vessel vasculitis (5 papers, 2017 to 2024). A type of vasculitis (inflammation of blood vessel walls) affecting large arteries such as the aorta and branches of the aorta. "For instance, in patients with large-vessel vasculitis, the detection of vascular inflammatory activity has been demonstrated with the first-generation TSPO-PET-Tracer [11C]-PK11195." (PMID 31960097, 2020). "TSPO molecular imaging using 11C-PK11195 provided valuable information such as presence, intensity, and localization of activated macrophages in large vessel vasculitis." (PMID 29114179, 2017). "In addition, a ligand for the translocator protein (TSPO) on activated macrophages, 11C-(R)-PK11195, was shown to improve imaging of macrophage infiltration to vessel wall in large- vessel vasculitis patients." (PMID 34768479, 2021).
malignant glioma (5 papers, 2015 to 2023). A grade III or grade IV glioma arising from the central nervous system. "Recently, the 18k-Da translocator protein (TSPO) targeted compounds have been shown to be highly accumulated in malignant gliomas by positron emission tomography." (PMID 36721481, 2023). "Radiotracers targeting the translocator protein (TSPO) have recently gained substantial interest, since TSPO is overexpressed in malignant gliomas, where it correlates inversely with patient’s survival." (PMID 35008218, 2021). "The functional relevance of TSPO is also reflected in its distinct expression levels within human diseases, including neurodegenerative disorders and malignant gliomas, where TSPO expression levels positively correlate with the malignancy of tumors." (PMID 33066460, 2020). "We thought that TSPO may be a novel target of BNCT for malignant glioma." (PMID 36721481, 2023). "Determining whether TSPO PET better delineates the true extent of tumor involvement as compared to MRI in patients with malignant glioma warrants further study, as it would have important clinical implications for detection, therapy planning, and post-treatment monitoring." (PMID 26517124, 2015). "In contrast, higher levels of TSPO expression were detected by IHC in the TMA containing high-grade, malignant glioma specimens." (PMID 26517124, 2015).
mood disorder (5 papers, 2016 to 2024). A cognitive disorder a disturbance in which the person's mood is hypothesized to be the main underlying feature. "The TSPO ligand used to activate TSPO could increase the activation of CREB and improved mood disorder as well as patient memory." (PMID 35285415, 2022). "Specific inflammatory markers such as TNF-α, IL-1β, CRP, and TSPO may be commonly involved in the pathogenesis of both SUD and mood disorders." (PMID 35558424, 2022).
pancreatic cancer (5 papers, 2022 to 2025). "Here, we investigate the contributions of TMEM97 and TSPO to S2R activity in MCF7 breast adenocarcinoma and MIA PaCa-2 (MP) pancreatic carcinoma cells." (PMID 37047353, 2023). "Several proteins with known roles in tumorigenesis such as FN1, TSPO, CD3E, and ZAP70 were present in the modules, which may be explored further as novel drug targets in pancreatic cancer." (PMID 36923555, 2022).
pulmonary diseases (5 papers, 2017 to 2023). "The TSPO-related effects may be particularly relevant to pulmonary diseases associated with CS, such as inflammation and cancer." (PMID 31295884, 2019).
alcohol use disorder (4 papers, 2018 to 2022). "Prossin and colleagues underlie how, within Bipolar patients, the presence or absence of the common, functional TSPO polymorphism (rs6971) may contribute to comorbidity of stress-exacerbated illnesses, including alcohol use disorders." (PMID 35893041, 2022). "The study concludes that, within Bipolar patients, the presence or absence of rs6971, the genetic variant of TSPO, may contribute to comorbidity of stress-exacerbated illnesses, including alcohol use disorders." (PMID 35893041, 2022). "Competition with an endogenous TSPO ligand would explain the discrepancy between current and prior in vivo findings and prior in vitro autoradiography findings in rat models of alcohol abuse; all of which found increased TSPO expression in hippocampus compared to non-drinking rats." (PMID 29777199, 2018).
Atrophy (4 papers, 2021 to 2025). Any weakening or degeneration, especially through lack of use. "SUVr of the predefined regions were correlated with disease-related parameters before and after PVEC to assess the influence of atrophy on associations between TSPO PET and clinical severity." (PMID 35203967, 2022). "The TSPO decreases we observed were not due to atrophy in males with ASD compared with controls, as volumes of affected brain areas were not abnormal in ASD, and the effect remained present after PVC." (PMID 32076115, 2021).
autism (4 papers, 2012 to 2021). Persistent deficits in social interaction and communication and interaction as well as a markedly restricted repertoire of activity and interest as well as repetitive patterns of behavior. "In our study, males with ASD exhibited lower regional TSPO expression compared with age-matched control males, with a trend for higher autism symptom severity to be associated with lower TSPO expression." (PMID 32076115, 2021). "Furthermore, in order to address the question of variability in TSPO expression across the autism spectrum and potential association with symptom severity, this work includes individuals with varying levels of functioning and disease severity." (PMID 32076115, 2021). "Decreased TSPO densities are difficult to interpret: it might be related to a physiological role of TSPO, and could in the case of autism reveal mitochondrial dysfunction, as suggested by the authors." (PMID 34387719, 2021). "The study aims were to assess whether young adult males with autistic disorder exhibit abnormal in vivo brain expression of TSPO using [11C]PBR28 PET imaging, and to determine whether TSPO expression is stable over a period of several months in both males with ASD and typically developing peers." (PMID 32076115, 2021).